LMNA (lamin A/C)
Diseases named in the same sentence as LMNA in open-access papers (continued):
Sharing a sentence is not in itself a finding about the gene and the disease.
Hutchinson-Gilford progeria syndrome (continued). "One of the most severe laminopathies, Hutchinson-Gilford progeria syndrome (HGPS), is predominantly caused by a de novo point mutation G608G (nucleotide 1824 C > T) in exon 11 of the LMNA gene encoding both LaminA and C isoforms." (PMID 34162976, 2021). "Most human progeroid syndromes result from monogenic defects in nuclear components (e.g. LMNA in Hutchinson-Gilford progeria syndrome, TERC in dyskeratosis congenita), and telomere length has long been observed as a marker of aging." (PMID 34467851, 2021). "Hutchinson-Gilford progeria syndrome (HGPS), a rare premature aging disorder that leads to death at an average age of 14.7 years due to myocardial infarction or stroke, is caused by mutations in the LMNA gene." (PMID 31635416, 2019). "The most characterized progeroid laminopathy is Hutchinson Gilford Progeria syndrome (HGPS), which is caused by a mutation in the LMNA gene generating a mutant lamin A indicated as progerin." (PMID 29936894, 2018). "Hutchinson-Gilford progeria syndrome (HGPS) is a fatal sporadic autosomal dominant premature ageing disease caused by single base mutations that optimise a cryptic splice site within exon 11 of the LMNA gene." (PMID 27920058, 2017). "Hutchinson-Gilford progeria syndrome (HGPS) is an extremely rare premature aging disease most commonly caused by a heterozygous mutation (c.1824C > T and p.G608G) in exon 11 of LMNA, the gene encoding the A-type lamins A and C." (PMID 26443848, 2015). "The AWS patients suffer the mutation of the lamin A/C gene (LMNA/C), the same causal gene seen in Hutchinson-Gilford progeria syndrome (HGPS)." (PMID 24799429, 2014). "Fibroblasts obtained from patients with Hutchinson-Gilford progeria syndrome (HGPS) and atypical Werner syndrome (AWS), each caused by mutations in the LMNA gene, were used to generate iPSCs." (PMID 23751357, 2013). "These morphological abnormalities are reminiscent of features of Hutchinson-Gilford Progeria Syndrome (HGPS), a rare premature aging disease caused by mutation in LMNA gene." (PMID 22783988, 2012). "The Hutchinson-Gilford progeria syndrome (HGPS) occurs, in most cases, through the de novo dominant LMNA p.G608G mutation, which results in the persistence of a truncated farnesylated prelamin A (lamin AΔ50, also called progerin)." (PMID 23285253, 2012). "In addition, the colocalization of LAP2α with telomeres and H3K27me3 undergoes attenuation in Hutchinson-Gilford Progeria Syndrome (HGPS), a condition caused by mutations in the LMNA gene." (PMID 39426946, 2024). "Next, we sought to investigate migrasome formation in other senescent hMSC models and turned to the Hutchinson-Gilford progeria syndrome (HGPS) model, in which premature aging characteristics are caused by a dominant-negative mutation in LMNA (c.1824 C > T; p.G608G)." (PMID 39872064, 2023). "Hutchinson-Gilford progeria syndrome (HGPS) is a pediatric progeroid disorder caused by a point mutation in LMNA (the gene for prelamin A and lamin C) that causes aberrant prelamin A splicing and the production of an internally truncated prelamin A protein (progerin)." (PMID 34423791, 2021). "The gene expression hypothesis has been studied extensively in the context of Hutchinson-Gilford progeria syndrome (HGPS), a premature aging syndrome caused by heterozygous LMNA mutations." (PMID 33030403, 2020). "Retention of this farnesylated C terminal domain by lamin A precursors is pathologic, and mutations in both the LMNA and ZMPSTE24 genes that cause this retention are implicated in premature aging disorders, such as Hutchinson-Gilford progeria syndrome (HGPS) and DCM." (PMID 31622279, 2019). "Individuals with Hutchinson-Gilford progeria syndrome (HGPS), caused by a point mutation in LMNA, the gene for the lamin A nuclear envelope protein, experience premature aging as a result of nuclear defects that lead to impaired cell division and transcriptional deregulation." (PMID 24757526, 2014).
Hutchinson-Gilford progeria syndrome (continued). "Lamin A (LMNA) is a component of the nuclear lamina and is mutated in several human diseases, including Emery-Dreifuss muscular dystrophy (EDMD; OMIM ID# 181350) and the premature aging syndrome Hutchinson-Gilford progeria syndrome (HGPS; OMIM ID# 176670)." (PMID 21464947, 2011). "Romedelin was originally shown to promote chromatin organization, nuclear architecture, and to decrease DNA damage markers in human lamin A/C-depleted cells and Hutchinson-Gilford Progeria Syndrome (HGPS)-derived patient cells." (PMID 37612540, 2023). "Furthermore, mutant LMNA might lead to aberrant protein expression; in addition, progerin is highly involved in the pathogenesis of the rare genetic premature aging syndrome Hutchinson-Gilford progeria syndrome (HGPS)." (PMID 34502359, 2021). "The features associated with LMNA loss-of function mutations arise from primarily affected MSCs and include reduction in muscle mass, defects of bone formation, and craniofacial symptoms, such as delayed closure of sutures as seen in mandibuloacral dysplasia (MAD) and Hutchinson-Gilford progeria." (PMID 29845577, 2018). "Other examples are the Hutchinson-Gilford Progeria (HGP) and Werner syndrome (WS), two premature aging disorders characterized by common natural aging already in childhood and attributed to mutations in the lamin A (LMNA) and the Werner syndrome RecQ helicase like (WRN) genes." (PMID 26974671, 2016). "The expression of the mutant gene LMNA is required for loss of telomeric length in this syndrome and it has been demonstrated that telomere length remains within the normal range in cells that do not express lamin A protein in Hutchinson-Gilford syndrome patients." (PMID 40231186, 2025). "For example, genes responsible for Werner syndrome (WS), Rothmund-Thomson syndrome (RTS), Bloom syndrome (BS), and Hutchinson-Gilford progeria syndrome (HGPS) are RECQ3 (WRN), RECQL4, RECQ2, and LMNA, respectively." (PMID 25365557, 2014). "Hutchinson-Gilford progeria (HGPS) is a rare premature aging disease, caused by a de novo point mutation in the lamin A gene LMNA G608G (GGC → GGT)." (PMID 33466669, 2021). "The serine-arginine (SR)-rich splicing factor 1 (SRSF1) controls LMNA pre-mRNA alternative splicing, leading to the production of progerin (the truncated prelamin A protein produced in HGPS (Hutchinson-Gilford Progeria Syndrome) cells and during physiological aging)." (PMID 28806747, 2017). "Less commonly, however, patients with LMNA mutations present with an early onset CAD and premature MI, typically in the context of progeroid syndromes, such as Hutchinson-Gilford Progeria Syndrome (HGPS) and atypical Werner syndrome, which typically involve multiple organs." (PMID 29047356, 2017).
cardiomyopathy (137 papers, 2007 to 2025). A disease of the heart muscle or myocardium proper. "While certain LMNA gene mutations are known to cause cardiomyopathy and conduction system disease, severe early-onset calcific valvular heart disease is not conventionally considered a typical feature of MADA." (PMID 41357091, 2025). "LMNA (lamin A/C) mutations are associated with a range of cardiomyopathies, including DCM, and can lead to fibrosis due to abnormal nuclear structure and function." (PMID 40291288, 2025). "Lamin A/C (encoded by LMNA) cardiomyopathy is a genetic disorder caused by mutations in the LMNA gene, which encodes the lamin A and C proteins." (PMID 40245468, 2025). "While cardiomyopathy and conduction system disease are recognized features of certain LMNA mutations, severe, early-onset calcific valvular heart disease is not conventionally considered part of the MADA phenotype." (PMID 41357091, 2025). "Studies have reported that increasing microtubule acetylation can restore cardiac dysfunction in atrial fibrillation, cardiomyopathies caused by LMNA mutations and cardiac proteotoxic disorders." (PMID 40245468, 2025). "We identified a four-generation family with LGMD and cardiomyopathy that was found to possess an LMNA mutation." (PMID 38732148, 2024). "This review will focus on the different cardiomyopathies caused by LMNA mutations, address the role of LMNA in chromatin organization and gene regulation, and discuss how these processes go awry in heart disease." (PMID 36899919, 2023). "Mutations in the LMNA gene cause heterogeneous phenotypes such as myopathy, progeroid syndromes, hereditary neuropathies, cardiomyopathies, or lipodystrophies." (PMID 37303410, 2023). "Rather, loss of mature lamin A due to homozygous null Lmna mutations in mice or LMNA haploinsufficiency in humans causes cardiomyopathy and muscular dystrophy." (PMID 37885131, 2023). "Since a number of LMNA mutations result in a loss of function, lamin A/C haploinsufficient (Lmna+/−) and Lmna knockout mice (Lmna-/-) have been extensively used to study the molecular mechanisms underlying LMNA loss-of-function (LOF) cardiomyopathy." (PMID 36899919, 2023). "Given the extremely poor prognosis of cardiomyopathy-causing in LMNA pathogenic variant carriers, early identification of affected family members is imperative." (PMID 37465451, 2023). "Of note, a very similar truncated variant of LMNA misplaced into the ER when expressed in cardiomyocytes but induced a severe cardiomyopathy by a different pathogenic mechanism." (PMID 37217929, 2023). "Among the many cardiomyopathy-associated genes is Lamin A/C (LMNA), one of the most sequenced human genes." (PMID 37123266, 2023). "Extensive studies have been conducted to examine mutations in the LMNA gene encoding prelamin A and lamin C, which result in distinct muscular dystrophy, cardiomyopathy, partial lipodystrophy, and progeroid syndromes." (PMID 37759521, 2023). "Overall, our work provides an adequate basis for testing these therapeutic approaches for patients with cardiomyopathy caused by mutations in LMNA." (PMID 36550158, 2022). "When compared with other known genetically-driven cardiomyopathies, those associated with LMNA mutations are associated with a poor clinical outcome." (PMID 35887646, 2022). "To determine the role of α-tubulin K40 acetylation in human disease, we next analyzed cardiac tissue from explanted hearts from patients with cardiomyopathy caused by mutations in LMNA following a heart transplant." (PMID 36550158, 2022). "The inherited disorders related to LMNA mutations include muscular dystrophies, cardiac conduction defects, and cardiomyopathy (such as DCM and ARVC/D)." (PMID 35526016, 2022). "The association between LMNA mutations, lipodystrophy and cardiomyopathy has been amply reported in the literature and the prevalence of all cardiac disorders increases with age." (PMID 35384599, 2022).
cardiomyopathy (continued). "SUMOylation of nuclear LMNA during DNA damage and replication stress facilitates nucleophagy, whereas cardiomyopathy‐related mutants of LMNA, such as K201R, E203G, and E203K, exhibit loss of SUMOylation." (PMID 36225129, 2022). "Further, we showed that elevation of α-tubulin acetylation levels with tubastatin A restored the correct localization of Cx43 at intercalated discs and improved cardiac function in a mouse model of cardiomyopathy caused by LMNA mutations." (PMID 36550158, 2022). "In summary, this work reveals how disruption of lamin A/C-dependent chromatin architecture in naïve pluripotent stem cells results in a cardiac disease phenotype and pinpoints key molecular determinants at the root of LMNA loss-of-function cardiomyopathies." (PMID 36333314, 2022). "One of the common cellular phenotypes observed in cardiomyopathy caused by mutations in LMNA is an abnormal elongation of nuclei in cardiomyocytes." (PMID 36550158, 2022). "Cardiomyopathy has not been reported to frequently occur in FPLD2 patients, as the FPLD mutation affects the C‐terminal domain of the LMNA gene, whereas cardiomyopathy mutations affect the rod domain." (PMID 35920656, 2022). "One of the interesting issues of our study was the early and initial development of AF and, up to this point, two family members had classical cardiomyopathy, over 60 years old, illustrating the age-dependent penetrance in the LMNA gene mutations." (PMID 35449878, 2022). "Based on these results we conclude that the novel LMNA variant resembles the severe pathogenic effect produced by LMNA-related cardiomyopathy." (PMID 35348702, 2022). "We conclude that disruption of lamin A/C-dependent chromatin architecture in ESCs is a primary event in LMNA loss-of-function cardiomyopathy." (PMID 36333314, 2022). "Any dysregulation in the LMNA gene is known to cause Hutchinson–Gilford progeria syndrome, cardiomyopathy, muscular dystrophy, emery-derifusss muscular dystrophy, and lipodystrophy." (PMID 34832615, 2021). "LMNA variants are associated with a broad spectrum of cardiomyopathies such as dilated cardiomyopathies, familial atrial fibrillation." (PMID 34642702, 2021). "Polymorphisms and mutations in the LMNA gene are known to be related to abdominal adipocyte size, type 2 diabetes mellitus and cardiomyopathy." (PMID 34627379, 2021). "The LMNA gene encodes lamin A/C protein, which constitutes the nuclear lamina and is a causative gene of not only cardiomyopathy but also myopathy, lipoatrophy, and progeria." (PMID 34830403, 2021). "Whole exome sequencing in PPCM patients revealed that in addition to an increase in pathological cardiomyopathy gene variants, such as LMNA mutation, also an increase in gene variants affecting the DNA damage response pathway are associated with PPCM." (PMID 32411727, 2020). "Some authors proposed a stratification of the risk of cardiomyopathy according to the type of LMNA mutations." (PMID 32245113, 2020). "The lipodystrophy syndromes practice guidelines remind us that in patients with atypical progeroid syndromes and FPLD2 due to LMNA mutations, cardiac abnormalities including ischemic heart disease, cardiomyopathy, arrhythmias and sudden death are reported." (PMID 32245113, 2020). "TTNtv are associated with incomplete penetrance and late onset heart failure, whereas patients with i.e., pathogenic RBM20 or LMNA mutations are affected by comparably early cardiomyopathies with incomplete penetrance." (PMID 33260757, 2020). "Genetic mutations associated with cardiomyopathy play a key role in disease formation, especially the mutation of sarcomere encoding genes and ATP kinase genes, such as titin, lamin A/C, myosin heavy chain 7, and troponin T1." (PMID 30995779, 2019). "Mutations in LMNA, which encodes the nuclear proteins Lamin A/C, can cause cardiomyopathy and conduction disorders." (PMID 31118417, 2019).
cardiomyopathy (continued). "LMNA encodes nuclear proteins lamins A and C for which mutations in this gene are associated with numerous diseases including cardiomyopathies, lipodystrophy, muscular dystrophies, and progeroid (early aging) syndromes, such as HGPS." (PMID 31921313, 2019). "Mutations in LMNA, encoding lamin A/C, cause cardiomyopathies, as well as Emery–Dreifuss muscular dystrophy (EDMD, MIM #181350)." (PMID 31718026, 2019). "We demonstrated that LMNA-KO rabbits exhibited almost all the hallmarks of the disease observed in the premature aging syndrome patients, including muscular dystrophy, cardiomyopathy, bone deficiency, lipodystrophy, and progeria." (PMID 30705772, 2019). "In that study, we compared normal human myoblasts with cells from type 2 Emery-Dreifuss muscular dystrophy (EDMD2), which is a disorder caused by LMNA mutations and characterized by muscle weakness, muscle wasting, and cardiomyopathy." (PMID 30326651, 2018). "Meanwhile, mutation of LMNA causes multiple human diseases including muscular dystrophy, cardiomyopathy, and lipodystrophy." (PMID 30505974, 2018). "Muchir and co-workers observed an activation of ERK, JNK and p38α cascades in hearts from LmnaH222P/H222P mice, linking the activation of MAPK pathways due to LMNA mutations to cardiomyopathy." (PMID 30425656, 2018). "A different pattern is observed in LMNA where haploinsufficiency causes phenotypes including cardiomyopathy, whereas specific missense variants result in lipodystrophy, and other specific mutations in LMNA cause distinct phenotypes, including progeria." (PMID 30020498, 2018). "This led to the first clinical trial in patients with cardiomyopathy caused by LMNA mutations using ARRY-371797 (NCT02057341)." (PMID 30425656, 2018). "A branch of the MAPK signaling cascade, the extracellular signal-regulated kinase (ERK), has been shown to be abnormally activated in cardiomyopathy associated with EDMD caused by mutations in the LMNA and EMD genes." (PMID 29192166, 2017). "Rapamycin-mediated mTORC1 inhibition rescues cardiac, skeletal muscle and adipose function and robustly enhances survival in Lmna−/− mice, a model for the cardiomyopathy and muscular dystrophy associated with human mutations in LMNA." (PMID 29736257, 2017). "Genetic screening of several cardiomyopathy genes, including LMNA, which is a causal gene for progeroid syndromes, led to identification of a very rare pathogenic p.Asp300Asn variant in the LMNA gene." (PMID 29047356, 2017). "A meta-analysis of 299 patients with an LMNA gene mutation suggested that cardiomyopathy due to LMNA mutations indicates a high probability of sudden death." (PMID 27649756, 2016). "Mutations in LMNA are much commonly reported to be associated with muscular dystrophy and/or cardiomyopathy than FPLD2." (PMID 27504462, 2016). "There are some LMNA mutations that are associated with early onset and severe cardiac disease including conduction system disease needing pacemaker implants and cardiomyopathy requiring transplantations." (PMID 27504462, 2016). "Recently, selumetinib was found to preserve cardiac function and improve survival in cardiomyopathy caused by mutation in the lamin A/C gene." (PMID 23702046, 2013). "The earliest cardiac finding in cardiomyopathy caused by a LMNA mutation is usually conduction system disease, associated with atrial or ventricular arrhythmias, atrioventricular (AV) conduction abnormalities and myocardial dysfunction." (PMID 21689390, 2011). "The present study demonstrates that 88% of asymptomatic or mildly symptomatic carriers of LMNA mutations causing cardiomyopathy had typical myocardial fibrosis, predominantly in the mid-myocardium of the basal septum." (PMID 21689390, 2011). "Interestingly, these nuclear abnormalities resemble those seen in lamin A/C-related disorders, which are associated with cardiomyopathies such as dilated cardiomyopathy and conduction system disease." (PMID 41423466, 2025).